YY1 (YY1 transcription factor)
Diseases named in the same sentence as YY1 in open-access papers (continued):
Sharing a sentence is not in itself a finding about the gene and the disease.
breast cancer (continued). "YY1 overexpression has been reported in virtually all cancer types, and its therapeutic target potential in breast cancer has been demonstrated using both in vitro assays and animal models." (PMID 34065631, 2021). "STAT3 suggested as a METTL8 transcription factor in the previous study, is shown to have a lower correlation than YY1 in breast cancer." (PMID 34063990, 2021). "A multivariate Cox regression model was employed to establish a predictive model containing 6 characteristic genes (HEY1, IFNA13, NKX2-3, NR2F1, POU5F1, and YY1) correlated with the prognosis of breast cancer." (PMID 34457116, 2021). "For example, it has been certified that LINC00673 activated by YY1 can facilitate breast cancer development by regulating Hippo signaling pathway." (PMID 34863279, 2021). "YY1 has been revealed to be highly expressed in various cancers, including prostate cancer, ovarian cancer, breast cancer, osteosarcoma, and melanoma." (PMID 34818994, 2021). "Collectively, our study indicates that METTL8 up-regulated by YY1 in breast cancer plays an important role in cancer cell migration through the mRNA modification of ARID1A, resulting in the attenuation of its translation." (PMID 34063990, 2021). "In summary, BCPRS and BCPRS-related genes (HEY1, IFNA13, NKX2-3, NR2F1, POU5F1, and YY1) can be used to evaluate the immune microenvironment and tumor purity in breast cancer patients." (PMID 34457116, 2021). "Encouragingly, YY1 has shown therapeutic effects in prostate cancer, hepatocellular carcinoma, breast cancer, cervical cancer, ovarian cancer, and multiple myeloma." (PMID 33985581, 2021). "We previously reported that both EZH2 and YY1 showed much lower expression in breast cancer cells than that in normal mammary cells, consistent with their important regulatory roles in mammary oncogenesis." (PMID 34065631, 2021). "For example, YY1 overexpression inhibits cell growth, foci formation and tumorigenesis in vivo in breast cancer." (PMID 34818994, 2021). "Expression of the six BCPRS genes (IFNA13, HEY1, NKX2-3, NR2F1, POU5F1, and YY1) in breast cancer tissues was analyzed using Tabula Muris's FACS and droplet methods." (PMID 34457116, 2021). "Our results suggest that the YY1-METTL8-ARID1A axis has an important role in breast cancer migration as well as in proliferation." (PMID 34063990, 2021). "YY1 mediates the migratory and invasive potential of breast cancer cells by recruiting and interacting with the PRMT7-HDAC3 complex." (PMID 32226547, 2020). "For example, YY1 activated the transcription of lnc00637 to promote the proliferation of breast cancer." (PMID 33135346, 2020). "In previous studies, YY1 can promote the initiation and development of human carcinomas, including breast cancer, nasopharyngeal carcinoma, glioblastoma, thyroid cancer, non-small cell lung cancer and so on." (PMID 32694944, 2020). "In the background of hormone therapy aimed at inhibiting estrogen production in breast cancer, YY1 contributes to clonal selection by maintaining the binding of ERα-YY1 to the enhancer of SLC9A3R1, a hormone therapy-resistant gene." (PMID 32226547, 2020). "The transcriptional repressive function of YY1 was further shown to result in suppression of breast cancer growth by direct repression of FEN1 gene and indirect repression of FEN1 through inducing miR-140 expression, which was shown to target FEN1 3′UTR." (PMID 31824839, 2019). "Several studies suggest both oncogenic and tumor suppressor function of YY1 in breast cancer progression." (PMID 31217904, 2019). "Aberrant expression of YY1 is frequently observed in a large number of cancers, such as colon, gastric and breast cancers." (PMID 31703732, 2019). "According to one report, YY1 is overexpressed in breast cancer tissue and its knock-down in breast cancer cell lines leads to reduction of clonogenicity, migration and invasion of cells." (PMID 31217904, 2019).
breast cancer (continued). "Inhibition of HSF1 blocked TGFβ‐, FAM3C‐ and YY1‐induced proliferation and migration of breast cancer cells." (PMID 30887707, 2019). "Interaction of YY1 with AP-2 transcription factor induces ERBB2 promoter activity in breast cancer cells." (PMID 31824839, 2019). "They, also, determined that the network of HDAC8 and YY1 prevents the proliferation of breast cancer cells." (PMID 31908740, 2019). "Ectopic overexpression of YY1 in breast cancer cell line MDA-MB-231 led to cell cycle arrest and reduced cellular growth in vitro and in vivo." (PMID 31217904, 2019). "Several studies demonstrated YY1 overexpression in breast cancer cell lines and primary tumors leading to tumor promotion." (PMID 31824839, 2019). "Collectively, the two sides of YY1 i.e., transcriptional activation and repression were shown to bring out the two sides of YY1 in breast cancer i.e., tumor promotion vs. tumor repression." (PMID 31824839, 2019). "In case of breast cancer and few other cancers, YY1 has been reported to play both a tumor promoter and a suppressor role, which is quite puzzling." (PMID 31824839, 2019). "Overall, these findings revealed that HSF1 is a direct target gene of YY1, which stimulated the proliferation and migration of breast cancer cells by inducing HSF1 expression." (PMID 30887707, 2019). "Different groups observed different outcomes for YY1 function in breast cancer and it is difficult understand how YY1 plays such opposing roles within a given cancer type." (PMID 31824839, 2019). "Mechanistically, YY1 has been shown to coordinate with AP2 to induce the oncogene Erbb2 in breast cancer cells leading to tumor aggressiveness." (PMID 31824839, 2019). "YY1 was found to be oncogenic in various types of cancers, such as breast cancer, prostate cancer and lymphomas." (PMID 29470526, 2018). "Specifically, studies have shown that YY1 is up-regulated in cervical cancer in addition to negatively regulating the expression of E-cadherin in the pathogenesis of breast cancer." (PMID 29470526, 2018). "In breast cancer, transcription factor Yin Yang 1(YY1) was suggested to be responsible for the reduced expression of HP1α." (PMID 29903985, 2018). "Overexpression of YY1 predicted poor prognosis in breast cancer and non-Hodgkin lymphoma, while the YY1 overexpression was found to be inversely correlated with poor prognosis in prostate cancer." (PMID 29470526, 2018). "In breast cancer, YY1 suppresses the expression of E-cadherin via NF-κB/Snail/YY1/RKIP/PTEN signaling, as well as via the methylation process." (PMID 29470526, 2018). "To further verify that YY1 binds to the hTERT promoter specifically in breast cancer, we also performed chromatin immunoprecipitation assay to detect the binding ability of YY1 to the endogenous hTERT promoter." (PMID 28492540, 2017). "Co-immunoprecipitation assay also confirmed the interaction between of NMI and YY1 in different breast cancer cells." (PMID 28492540, 2017). "Further mechanistic insights demonstrated that NMI functioned to regulate hTERT through its interaction with YY1 in breast cancers." (PMID 28492540, 2017). "Reduction of YY1 levels in breast cancer cells results in overexpression of FEN1 leading to resistance to chemotherapeutic drugs." (PMID 25885449, 2015). "Accordingly, elevated YY1 level were consecutively found in ovarian cancer, breast cancer, cervical cancer, and osteosarcoma." (PMID 26104682, 2015). "The increased expression of YY1 was reported in prostate cancer, colon cancer, ovary cancer, breast cancer, skin cancer, cervix cancer, bladder cancer, bone cancer, liver cancer, and lung cancer." (PMID 25053986, 2014). "In breast cancer, for instance, YY1 positively regulates the expression of breast cancer-associated gene 1 (BRCA1) and heterochromatin protein 1 (HP1)." (PMID 24674326, 2014).
breast cancer (continued). "Significantly, YY1 expression was detected to be lower in the invasive breast cancer cell line, implicating its role in the reduction of HP1α expression and possibly in the acquisition of an invasive phenotype." (PMID 19566924, 2009). "We tested the effect of YY1 overexpression on both migration and invasion of the invasive breast cancer cell line HS578T." (PMID 19566924, 2009). "YY1 has also been implicated in the negative regulation of the chemokine receptor CXCR4, which has been implicated in the ability of breast cancer cells to metastasize to bone." (PMID 19566924, 2009). "It has recently been proposed that the transcription factor AP-2α and its cofactor, YY1, can induce HER2 gene transcription independently of HER2 gene mutation in breast cancer." (PMID 20025767, 2009). "For this reason we investigated discordant HER2 gene and protein expression and the association between the transcription factors AP-2 and YY1 and their association with HER2 in a large population of well characterised breast cancer patients." (PMID 20025767, 2009). "In the largest study of patients with primary operable breast cancer to date, we characterised two isoforms of the transcription factor AP-2, namely AP-2α/β and AP-2α, and its cofactor YY1." (PMID 20025767, 2009). "In this report, we examined the relationships between ERBB2, AP-2α, and YY1 both in breast cancer tissue specimens and in a mammary cancer cell line." (PMID 18218085, 2008). "The functional role of AP-2α and YY1 on ERBB2 gene expression was analyzed by small interfering RNA (siRNA) transfection in the BT-474 mammary cancer cell line followed by real-time reverse transcription-polymerase chain reaction and Western blotting." (PMID 18218085, 2008). "We first detected levels of ERBB2, AP-2α, and YY1 proteins by immunohistochemistry (IHC) in tumor specimens from 55 cases of breast carcinomas." (PMID 18218085, 2008). "This suggests YY1 may contribute to an immunosuppressive tumor microenvironment as seen in breast cancer models where naive CD4 + T cells were found to convert to regulatory T cells supporting immunosuppression." (PMID 41327312, 2025). "Furthermore, YY1 knockdown altered the architecture of breast cancer cells, making them resemble normal breast epithelial cells, while its overexpression induced malignant features in nontumorigenic cells." (PMID 41327312, 2025). "However, due to the conflicting roles of YY1 in different breast cancer subtypes and cellular contexts, further research is needed to define its mechanistic contributions to tumor progression, immune modulation, and therapy resistance." (PMID 41009346, 2025). "In addition to gene expression profiles, we explored the prognostic impact of YY1 in breast cancer using the KM plotter and GENT2 platforms." (PMID 41009346, 2025). "In addition, a study on breast cancer tissue revealed another small molecule that can directly regulate YY1, betulinic acid." (PMID 41327312, 2025). "In contrast, other studies have suggested an opposite role for YY1 in breast cancer prognosis." (PMID 41009346, 2025). "The transcription factor YY1 has gained attention as a potential oncogenic driver, given its upregulation in several tumor types, including acute myeloid leukemia and colon, liver, and breast cancers." (PMID 41009346, 2025). "Although transcription factor YY1 regulates METTL8 expression in breast cancer cells and STAT3 transcriptionally activates METTL8 in mouse embryonic stem cells, the upstream regulator of METTL8 in GBM remains unknown." (PMID 38744809, 2024). "Furthermore, YY1 depletion has also been shown to stop growth in soft agar in vitro of bladder, prostate, lung, and breast cancer cell lines." (PMID 39796650, 2024). "However, it is important to note here that YY1 protein expression levels in breast cancers are regulated at both transcriptional and post-transcriptional levels." (PMID 37444605, 2023).
breast cancer (continued). "However, the suppressive effect of the YY1/miR-873-5p axis on the stemness of breast cancer cells can be reversed by inhibiting the PI3K/AKT and ERK1/2 pathways." (PMID 37444616, 2023). "Our previous study also probed that some TFs, including Yin Yang 1 (YY1), as a molecular target for basal-like breast cancer, could promote epithelial-to-mesenchymal transition progression of the basal-like subtype through trans-activating the Kinectin 1 gene." (PMID 36814821, 2023). "Another example of the lncRNA regulation upon YY1 was reported in breast cancer." (PMID 37444616, 2023). "Of 491 patients with primary breast cancer, 138 patients showed YY1 overexpression." (PMID 37444605, 2023). "The YY1 has been identified extensively overexpressed in malignant tumors including breast cancer." (PMID 35383155, 2022). "As RNF144A is downregulated in breast cancer cell lines and tumor tissues, which could be partially contribute to overexpression of YY1 in breast cancer cells." (PMID 35103856, 2022). "In breast cancer, YY1 functions as an oncogene and negatively regulates p27 expression." (PMID 35103856, 2022). "The transcription factor Yin Yang 1 (YY1) is upregulated in high‐grade breast cancer." (PMID 35811688, 2022). "In conclusion, the findings presented in this study suggest that RNF144A exerts tumor suppressor functions in breast cancer cells through targeting transcription factor YY1 for proteasomal degradation, thus blocking YY1-mediated transcriptional activation of GMFG expression in breast cancer cells." (PMID 35103856, 2022). "Interestingly, NMI can also negatively regulate the expression of hTERT in breast cancer through the Yin Yang 1 (YY1) protein, to control tumor growth." (PMID 36506566, 2022). "The S118 site of YY1 implied higher phosphorylation expression in breast cancer, colon cancer, uterine corpus endometrial carcinoma (UCEC), and lung adenocarcinoma (LUAD) tumor tissues, but lower phosphorylation levels in ovarian cancer and clear cell carcinoma tumor tissues." (PMID 35791393, 2022). "YY1 could promote the cell proliferation of breast cancer cells by inhibiting the expression of a cell cycle inhibitor." (PMID 35359580, 2022). "Finally, immunohistochemical analysis showed higher YY1 levels in significant proportions of breast cancer, colorectal cancer, and lymphoma." (PMID 35791393, 2022). "Besides, even in breast cancer, YY1 has been reported with two-side effects (cancer suppression/cancer progression)." (PMID 35383155, 2022). "This may support our result showing that, instead of STAT3, YY1 is a more important transcription factor regulating METTL8 expression in breast cancer." (PMID 34063990, 2021). "In addition, when we compared the correlation of the gene expression patterns between METTL8 and putative transcription factors, YY1 showed a better correlation coefficient in breast cancer compared to other putative transcription factors." (PMID 34063990, 2021). "YY1-mediated EZH2 activity is essential to gene expression; thus, we predicted that disruption of their interaction could cause perturbation in breast cancer cells and thus inhibit cancer progression." (PMID 34065631, 2021). "Therefore, a neural network-based model was constructed to predict cell types in breast cancer tissues based on genes YY1, POU5F1, NKX2-3, NR2F1, HEY1, and IFNA13." (PMID 34457116, 2021). "In addition, THRAP3, TARDBP, and YY1 were the most stably expressed genes in the breast cancer cell lines, while B2M, TUBA1A, and ACTB were the least stably expressed genes." (PMID 34895237, 2021). "Some studies revealed that YY1 is overexpressed in breast cancer, correlating with poor prognosis." (PMID 32806777, 2020).
breast cancer (continued). "Herein, YY1 had been known to have two sides, a tumour promoter and a tumour suppressor, in various kinds of cancer types, such as breast cancer and lung cancer, depending on the cancer type and its interacting partners by regulating the expression or repression of related genes." (PMID 32557953, 2020). "Moreover, YY1-activated LINC00673 has been revealed to promote proliferative activity of breast cancer cells via regulating MARK4 through sponging miR-515-5p." (PMID 32272940, 2020). "However, even though many studies report YY1 as an oncogenic protein in many cancers, in breast cancer it has a controversial role as an oncogene or oncosuppressor." (PMID 32806777, 2020). "Interaction of YY1 with AP-2 transcription factor induces ERBB2 expression in breast cancer cells." (PMID 31824839, 2019). "Hence, YY1-dependent repression of FEN1 leads to sensitization of breast cancer cells to DNA-damaging agents." (PMID 31824839, 2019). "Furthermore, FEN1 was found be regulated by the transcriptional repressor Ying Yang 1 (YY1) in response to DNA damaging agents in the context of breast cancer." (PMID 31534853, 2019). "HSF1 inhibition also repressed YY1‐induced migration of breast cancer cells." (PMID 30887707, 2019). "Interestingly, in the case of breast cancer, it is quite puzzling that YY1 functions as both tumor promoter and tumor suppressor." (PMID 31824839, 2019). "In this context, it is perhaps likely that specific interacting partners of YY1 might be either missing or overexpressed within different breast cancer patients and hence the opposing outcome." (PMID 31824839, 2019). "Hence, most likely, NMI cooperates with YY1 to downregulate hTERT transcription and expression and thereby inhibit the stemness and growth of breast cancer cells." (PMID 28492540, 2017). "Moreover, the involvement of YY1 protein in NMI-mediated transcriptional regulation of hTERT in breast cancer was identified and confirmed." (PMID 28492540, 2017). "In that cohort, patients with FEN1-high and YY1-low expression had both statistically significantly poor overall and disease-free postoperative survivals, a fact suggesting that FEN1 and YY1 might have inverse impact on the survival of breast cancer patients." (PMID 25885449, 2015). "We find that the YY1 site overlapping the risk SNP is occupied in a prostate but not a breast cancer cell line and propose that this binding of YY1 in prostate cells mediates transcriptional repression that is influenced by the presence of the SNP." (PMID 21814516, 2011). "Candidacy for anti-HER2 adjuvant therapy in breast cancer is assessed using tumour HER2 status but recently it has been proposed that the transcription factors AP-2α and YY1 may cause Her2 protein overexpression independently of gene amplification." (PMID 20025767, 2009). "Our data suggests that a reduction of YY1 expression in breast cancer cells could contribute to the acquisition of an invasive phenotype through increased cell migration as well as by reduced expression of HP1α." (PMID 19566924, 2009). "In addition, the clinicopathological value of AP-2 and YY1 in breast cancer was assessed in view of the previous conflicting reports and its proposed role as a possible therapeutic target in breast cancer." (PMID 20025767, 2009). "We conclude that decreased YY1 expression may contribute to the invasive phenotype of metastatic breast cancer cells." (PMID 19566924, 2009). "Next, we wanted to know if YY1 expression correlates with breast cancer cell invasiveness." (PMID 19566924, 2009). "Our data suggest that YY1 acts as a suppressor of migration in breast cancer cells." (PMID 19566924, 2009). "High AP-2α and YY1 protein levels were seen in 42% and 45% of breast carcinomas, respectively." (PMID 18218085, 2008).